VEGFA (vascular endothelial growth factor A)
Diseases named in the same sentence as VEGFA in open-access papers (continued):
Sharing a sentence is not in itself a finding about the gene and the disease.
periodontitis (54 papers, 2014 to 2025). An acute or chronic inflammatory process that affects the tissues that surround and support the teeth. "In addition, certain identified biomarkers, including IL8, IL1β, ICAM1 and VEGFA, were hub genes, therefore suggesting that they may be useful diagnostic markers for periodontitis." (PMID 25483140, 2015). "PDLSCs derived from patients with periodontitis secrete more exosomes enriched with increased amounts of vascular endothelial growth factor A (VEGFA), a key pro-angiogenic protein." (PMID 41322905, 2025). "Vascular specific marker CD31 and VEGFA were found to be highly expressed in periodontal ligaments of periodontitis." (PMID 32210705, 2020). "Compare with control group, the positive areas of CD31 and VEGFA were larger in gingiva of periodontitis group, as well as the overlapped area of the two markers." (PMID 32210705, 2020). "The VEGFA was up-regulated in PDLSCs derived from periodontitis and PDLSCs treated with inflammatory factors compared to control group." (PMID 32210705, 2020). "In conclusion, the findings indicated that vascularization of periodontal ligaments was enhanced, and inflammatory micro-environment of periodontitis facilitated pro-angiogenesis of PDLSCs through regulating exosome-mediated transfer of VEGFA, which was targeted by miR-17-5p." (PMID 32210705, 2020). "In our study, VEGFA, the vascular specific marker, was up-regulated in PDLSCs derived from periodontitis, suggesting that inflammation might affect the pro-angiogenesis of PDLSCs." (PMID 32210705, 2020).
cerebral infarction (53 papers, 2009 to 2025). An ischemic condition of the brain, producing a persistent focal neurological deficit in the area of distribution of the cerebral arteries. "The results indicated that JCT could treat ICS by reducing the symptoms of cerebral infarction and enhancing neuroprotective effects, and its action mechanisms were associated with the activation of the HIF-1α/EPO/VEGFA pathway." (PMID 36269045, 2022).
liver disease (53 papers, 2010 to 2025). "VEGF mRNA-LNP robustly induced the BEC-to-hepatocyte transdifferentiation and promoted the recovery of liver function in both chronic and acute mouse liver injury models, suggesting the potential clinical benefits of VEGFA mRNA-LNP to alleviate liver diseases." (PMID 39544362, 2024).
anemia (52 papers, 2010 to 2025). A reduction in the number of red blood cells, the amount of hemoglobin, and/or the volume of packed red blood cells. "Using the minimal anemia-correcting dose of DPD, we observed an elevation of the mRNA level of the HIF target genes Glut1 and VEGFA in both the kidney and the aorta." (PMID 39144616, 2024).
acute kidney injury (51 papers, 2009 to 2026). Sudden and sustained deterioration of the kidney function characterized by decreased glomerular filtration rate, increased serum creatinine or oliguria. "Furthermore, miR‐195 suppresses inflammatory cytokine production and oxidative stress by regulation of vascular endothelial growth factor A in acute kidney injury." (PMID 34850451, 2022). "Studies have shown that targeting VEGFA can regulate the STAT3 signaling pathway to inhibit inflammation and oxidative stress, thereby delaying the progression of hyperuricemia-induced chronic dilatation renal fibrosis, improving renal failure, and reducing serum UA levels." (PMID 38257230, 2024).
adenoma (51 papers, 2006 to 2025). A neoplasm arising from the epithelium. "For instance, VEGFA is upregulated in adenomas and carcinomas, whereas VEGFD is more abundant in normal tissues." (PMID 27148488, 2016). "Increased TBP expression in adenomas may produce a constitutive increase in VEGFA expression that then primes these tissues for a more robust VEGFA induction under hypoxic conditions to generate an angiogenic switch." (PMID 28415573, 2017). "In addition, MMP2, SNAI1, and VEGFA contributed to proliferation and invasion of adenomas." (PMID 33425722, 2020). "Of note, VEGFA, VEGFB, VEGFC, and VEGFD expression is modulated during the adenoma–carcinoma sequence in CRC." (PMID 27148488, 2016).
thrombotic microangiopathy (51 papers, 2010 to 2026). The syndromes of microangiopathic hemolytic anemia, thrombocytopenia, and variable signs of organ impairment, due to platelet aggregation in the microcirculation. "It has been reported that VEGFA inhibition or reduction could result in thrombotic microangiopathy with renal involvement." (PMID 31071929, 2019). "Podocyte-specific vascular endothelial growth factor-A (VEGFA) knockout mice developed marked proteinuria and the kidneys showed thrombotic microangiopathy (TMA), a lesion characterized by fibrin platelet thrombus formation." (PMID 36744132, 2023).
type 1 diabetes (51 papers, 2011 to 2025). "Research in a type 1 diabetic mouse model has indicated that a local decrease in glomerular vascular endothelial growth factor A (VEGFA) exacerbates endothelial damage and hastens glomerular injury progression." (PMID 40690456, 2025). "However, their diabetic model was type 1 diabetes, and they merely assessed VEGFA expression in mouse eyes." (PMID 33062917, 2020). "Furthermore, the expression of vascular endothelial growth factor A and its receptors was significantly increased, especially in type 1 diabetes, compared with nondiabetic patients, suggesting a space-filling vascular growth, leading to increased nerve compression in the carpal tunnel." (PMID 40520543, 2025).
hemorrhage (50 papers, 2007 to 2026). Loss of blood from the vascular compartment to the exterior or into nonvascular body space as a result of rupture or severance of the blood vessels. "Twelve single nucleotide polymorphisms (SNPs), including IL6 rs1800795, IL17A rs2275913, MMP9 rs9509, VEGFA rs1547651, and EPHB4 rs314353, rs314308, and rs314313, were associated with bAVM-related hemorrhage." (PMID 37065486, 2023). "This led to the identification of statistically significant association between bAVM-related hemorrhage and twelve heritable variants of seven genes (IL6, APOE, IL1B, IL17A, MMP9, EPHB4, and VEGFA) involved in the inflammatory and angiogenic signaling pathways." (PMID 37065486, 2023). "At the time of plasma leakage, elevated levels of permeability-enhancing factors, tumor necrosis factor-α (TNF-α) and vascular endothelial growth factor-A (VEGFA) are found in severe dengue patients and contribute to three main pathological features: plasma leakage, hemorrhage and coagulopathy." (PMID 32545679, 2020).
rectal cancer (50 papers, 2002 to 2026). A primary or metastatic malignant neoplasm that affects the rectum. "We found that MMP9, MYC, and VEGFA were upregulated in the rectal cancer group compared with normal tissue." (PMID 28689994, 2017). "In 25 patients with locally advanced rectal cancer (LARC), we evaluated QFE targeting vascular endothelial growth factor A (VEGFA) to detect residual tumour after neoadjuvant chemoradiotherapy (nCRT)." (PMID 31533965, 2020).
colorectal tumor (49 papers, 2002 to 2026). "It downregulated receptor tyrosine kinases and vascular endothelial growth factor A (VEGF-A) in a colorectal tumor xenograft model." (PMID 33466486, 2021). "However, from TNM database it is evident that expression of HIF1α and VEGFA is significantly (p = 3.48e−04 and 1.23e−113) higher in colorectal tumor tissues compared to the normal tissues." (PMID 40045186, 2025). "Given our findings that TBP regulates VEGF expression, we compared relative TBP and VEGFA expression in normal tissue and colorectal tumors in the five publicly available datasets as they were all shown to have increased TBP in tumors compared to the normal tissues." (PMID 28415573, 2017). "In addition, immunohistochemistry for vascular endothelial growth factor-A and interleukin-6 was performed on colorectal tumours of such patients." (PMID 12454774, 2002). "For the two colorectal tumor cell lines HCT-116 and HT-29 (CRC) VEGFA was upregulated to a similar extent under hypoxic conditions with 2.5-fold (p = 0.008) and 2.4-fold (p = 0.007)." (PMID 24059699, 2013). "Furthermore, inhibition of IL-1 signaling by Anakinra decreased NOTCH1, JAGGED1, IL-1β, LEPTIN, ObRb, VEGFA, VEGFR1, and VEGFR2 expressions in colorectal tumors." (PMID 38152619, 2023).
gastric tumor (49 papers, 2011 to 2025). "We have previously demonstrated that the VEGFA-driven angiogenic stimulus reduces Multimerin-2 expression, thus the loss of Multimerin-2 in gastric tumor vessels may be due to the high levels of VEGFA often found in gastric tumors." (PMID 30544909, 2018). "For example, cyclic AMP response element binding protein 3-like 4 (CREB3L4) promotes the progression of gastric tumors and endothelial angiogenesis by transcriptionally activating the VEGFA promoter." (PMID 34233659, 2021). "Precisely, PVT1 expression in gastric tumors enhances microvessel formation, both in vitro and in vivo, through a mechanism that involves vascular endothelial growth factor A (VEGFA) expression in a STAT3-dependent manner." (PMID 32083000, 2020). "Moreover, NDV-D90 appeared to reduce gastric tumor vascularization, possibly through suppression of vascular endothelial growth factor A (VEGF-A) and Matrix Metallopeptidase 2 (MMP-2)." (PMID 28388537, 2017). "Interestingly, Serpin E1 also stimulates VEGFA expression in CAFs in vitro, suggesting that both HUVECs and CAFs may serve as the primary sources of VEGFA within the gastric tumor microenvironment infected by H. pylori." (PMID 38104099, 2023). "The expression of ACTA2, HIF1A, and VEGFA was independently associated with TJP1 in non-cancerous tissue, explaining 90% in its variability, and BCL2, HIF1A, CDKN1A, and PTGS2 were independently associated with TJP1 in gastric tumors, explaining 98% in gene variability." (PMID 32630408, 2020).
kidney cancer (49 papers, 2010 to 2025). Primary or metastatic malignant neoplasm involving the kidney. "Kidney cancer cells overexpress several redundant pro-angiogenic factors, including VEGFA and the cytokine CXCL8, compared to healthy tissues." (PMID 37508458, 2023). "In experimental kidney cancer in mice, anti-VEGFA accelerates tumor growth but when combined with an anti-CXCL8 antibody, tumor growth is inhibited." (PMID 37508458, 2023). "A study reported that TGF-β differentially influenced the expression of VEGFA in kidney cancer cell lines." (PMID 35625561, 2022). "Targeted drugs for VEGFA have been studied in kidney cancer." (PMID 38944814, 2024). "Particularly, high‐throughput sequencing data revealed that JMJD6 could assemble super‐enhancers to drive a list of identity genes in kidney cancer, including VEGFA, β‐catenin, and SRC." (PMID 33634984, 2021). "P300‐activated JMJD6 may constitute SEs to drive a series of kidney cancer‐related drivers, such as VEGFA, β‐catenin, or SRC." (PMID 33634984, 2021). "In cellular models of kidney cancer, BVZ traps VEGFA and increases the compensatory production of pro-angiogenic ELR+CXCL cytokines." (PMID 37508458, 2023). "The 26 down-regulated microRNA had 170 direct up-regulated mRNA targets, including oncogenes VEGFA, LOX, LOXL2 and FAS, well known to be involved in kidney cancer." (PMID 20420713, 2010).
cholangiocarcinoma (48 papers, 2009 to 2026). A carcinoma that arises from the intrahepatic biliary tree (intrahepatic cholangiocarcinoma) or from the junction, or adjacent to the junction, of the right and left hepatic ducts (hilar cholangiocarcinoma). "A different study demonstrated that MACC1 promotes angiogenesis in cholangiocarcinoma by upregulating VEGFA expression." (PMID 33425885, 2020). "An experimental research has verified that interactions of LOXL2 with GATA6 can induce the expression of VEGFA, which may promote angiogenesis in cholangiocarcinoma subcutaneous tumorsand tumor growth." (PMID 33478536, 2021). "Furthermore, CCA cells also express vascular endothelial growth factor A (VEGFA) which is correlated with increased vascular density which in turn correlates with cancer progression, metastasis, and prognosis in intrahepatic and hilar cholangiocarcinoma." (PMID 34577598, 2021). "Notably, VEGFA and CXCL8 exhibited higher protein expression in HCC and cholangiocarcinoma tumor tissues compared with normal liver tissue." (PMID 41514936, 2026). "In addition to suppressing cholangiocarcinoma cell proliferation, migration, and invasion, menin also suppresses the expression of pro-angiogenic factors such as VEGFA/C, VEGFR2/3, angiopoietins-1/2, and angiopoietin receptors TIE1/2 in a cholangiocarcinoma cell line and tumor xenograft model." (PMID 39336822, 2024). "In OS, we observed that MACC1 depletion had a modest effect on VEGFA expression levels (data not shown), suggestive of a differential regulatory mechanism for MCCA1 between OS and cholangiocarcinoma." (PMID 33425885, 2020).
lung disease (47 papers, 2006 to 2026). "In the context of human lung disease, prior studies have demonstrated alterations in VEGFA signaling and blood vessel biology in smokers with and without COPD." (PMID 33731767, 2021).
Infertility (46 papers, 2010 to 2026). "Our study revealed that the KDR gene rs2071559 variant may be associated with infertility and rs699947 VEGFA with an increased risk of recurrent implantation failures in infertile ART treated Polish women." (PMID 36901702, 2023). "Endometrial expression of LIF and VEGFA is altered in diabetic rats during implantation which may be associated with diabetic-related infertility." (PMID 33062917, 2020). "The expressions of LIF and VEGFA were altered in diabetic rats during implantation which may be associated with diabetic-related infertility." (PMID 33062917, 2020). "VEGFA, a downstream target of HIF-1α, associated with infertility in mice, exhibited increased expression in the seminiferous tubules of FD patients, consistent with our immunofluorescence and RT-PCR results." (PMID 38455658, 2024). "In humans, VEGFA expression level is higher in uterine fluid samples from fertile than infertile women during the implantation window." (PMID 30515407, 2018). "Our findings suggest that VEGFA could potentially serve as an early marker for testicular inflammation, subfertility, and infertility." (PMID 38255715, 2024). "Analysis of the dataset of infertile cases and controls revealed synergistic interactions between KDR rs2071559 and KDR rs1870377 (IG = 1.86%) and KDR rs1870377 and VEGFA rs699947 (IG = 1.13%)." (PMID 36901702, 2023). "By analyzing DEGs, molecular docking and ADMET properties, we suggest that identified hub proteins, especially VEGFA and PIK3R1 can be used as a target to treat infertility mediated cancer progression." (PMID 36608061, 2023). "Here, we report that endometrial upregulation of HIF1α, VEGFA, and VEGFR2, as well as excessive vascularization in the peri-implantation endometrium, may reduce endometrial receptivity in infertile CE patients." (PMID 36531509, 2022). "Molecular docking and ADMET properties against VEGFA (PDB ID: 1FLT) and PIK3R1 (PDB ID: 5M6U) showed sesamin, galangin, and coumestrol were the top three compounds that might play a role on therapeutic target in the treatment of infertility and infertility mediated cancer progression." (PMID 36608061, 2023).
prostate tumors (46 papers, 2003 to 2025). "The MCP-1, in turn, acts in an autocrine manner through CCR2 on prostate tumour cells, stimulating the release of vascular endothelial growth factor-A (VEGF-A)." (PMID 31713180, 2019). "Bender and co-workers speculated that primary prostate tumors experiencing VEGFA (vascular endothelial growth factor-A) low expression." (PMID 35456461, 2022). "In addition, the results from several preclinical studies indicate that VEGFA inhibition or treatment with anti-VEGFA antibodies blocks the growth of human prostate tumors through suppression of angiogenesis, further supporting the role of VEGFA-mediated angiogenesis in PCa growth and progression." (PMID 32842503, 2020). "Both human PCa and PCa tissues of animal origin, including prostate tumors isolated from TRansgenic Adenocarcinoma Mouse Prostate (TRAMP)models, show an increased expression of VEGFA in comparison to normal prostate tissues." (PMID 32842503, 2020).
vascular tumors (46 papers, 2009 to 2025). "Furthermore, the majority of tumors displayed evidence of VEGFA expression, in line with the concept that GEPNETs are highly vascular tumors, and VEGFA expression and microvascular count seem to paradoxically reduce with progressive tumor de-differentiation in PanNETs." (PMID 36139632, 2022).
angiosarcoma (45 papers, 2006 to 2025). A malignant tumor arising from the endothelial cells of the blood vessels. "Expression of cyclin D1 (CCND1), a cell proliferation marker, VEGFA and VEGF165 (a splice variant of VEGFA), potent inducers of angiogenesis, was significantly higher in angiosarcoma cells than in normal endothelial cells and HAMON cells showed higher expression than ISO-HAS-B." (PMID 35256687, 2022). "In our exploration of the genetic landscape of canine hemangiosarcoma, we focused on identifying copy number alterations (CNAs) within genes previously associated with the disease, including CDKN2A/B, VEGFA, KDR, SKI, MYC, and KIT." (PMID 39872607, 2024). "Furthermore, our CNA analysis identified significant genomic regions linked to hemangiosarcoma pathogenesis, such as alterations in CDKN2A/B, VEGFA, KDR, MYC, and KIT." (PMID 39872607, 2024). "Vessel formation in hemangiosarcoma resembles the morphology of imbalanced, chaotic growth and maturation of neoangiogenic vessels seen in cancer, which is at least partly driven by pro-angiogenic factors such as vascular endothelial growth factor-A (VEGF)." (PMID 21062482, 2010). "In the case of reduced or absent CD31 immunoreactivity in a suspected hemangiosarcoma, additional immunohistochemistry can be performed, including von Willebrand factor, vascular endothelial growth factor A, or angiopoietin-2." (PMID 37104402, 2023). "Indeed, compared to other sarcomas, angiosarcoma tumors exhibited higher expression levels of endothelial marker/functional genes including PECAM1, EPHA2, ANGPT2, ENDRB, PGF, FLI1, VWF and reduced expression levels in KIT, VEGFA, and VEGFB." (PMID 25374893, 2013).
esophageal squamous cell carcinoma (45 papers, 2013 to 2025). Esophageal squamous cell carcinoma (ESCC) is a type of esophageal carcinoma (EC) that can affect any part of the esophagus, but is usually located in the upper or middle third. "Given that, our study investigated the role of LINC00662 from esophageal squamous cell carcinoma (ESCC) cells-derived extracellular vehicles (EVs) in angiogenesis through microRNA (miR)-195-5p/vascular endothelial growth factor A (VEGFA) axis." (PMID 35433661, 2022). "A total of 108 esophageal squamous cell carcinoma tissues were immunohistochemically stained with blood vessel markers and angiogenesis-related markers, including CD31, alpha smooth muscle actin, vascular endothelial growth factor A (VEGF-A), CD206, and D2-40." (PMID 40640482, 2025).